CD46 (CD46 molecule)
Diseases named in the same sentence as CD46 in open-access papers (continued):
Sharing a sentence is not in itself a finding about the gene and the disease.
preeclampsia (10 papers, 2011 to 2025). Preeclampsia is a hypertensive disorder of pregnancy that is characterized by new-onset hypertension with proteinuria presenting after 20 weeks of gestation, and depending on mild or severe forms may initially present with severe headache, visual disturbances, and hyperreflexia. "These patients have higher complement mutation frequency, including rare germline mutations in the alternative CS pathway (CFHR1, CFHR3, CFI, CFB, and CD46) than women with preeclampsia, having similar rates of variants as the control population." (PMID 40904461, 2025). "Together, these data suggested that complotypes consisting of homozygous genotypes of fetal CD46 SNPs and heterozygous/homozygous genotypes of maternal factor H or C3 predisposed women to develop preeclampsia." (PMID 32179765, 2020). "We speculated whether the CD46 variant could be a novel cause of failure of anti-D Ig prophylaxis and potentially explain the postpartum signs of preeclampsia, which may have aggravated the perinatal stress tCHI." (PMID 34838142, 2021). "Several recent studies indicating elevated C3a, increased placental MAC deposition and association between CD46 mutations and preeclampsia suggest that in preeclampsia patients complement activation is increased at the feto-maternal interface possibly secondary to defective regulation." (PMID 32745140, 2020). "Interestingly, Salmon and co-workers reported CD46 mutations as genetic defects associated with preeclampsia." (PMID 25710174, 2015). "The missing association between CD46 mutations and preeclampsia may also be attributed to incomplete penetrance of complement mutations in preeclampsia." (PMID 25710174, 2015). "In this study we have explored the genetic polymorphism of CD46 in preeclampsia." (PMID 25710174, 2015). "Indeed mutations in genes encoding complement inhibitor CD46 are associated with development of preeclampsia, supporting dysregulation of complement activation at least at the CD46 step as a risk factor for preeclampsia." (PMID 26556948, 2015). "Membrane cofactor protein MCP (CD46) is among the potent complement regulators that have recently been linked to a severe form of preeclampsia with or without an underlying autoimmune phenotype." (PMID 25710174, 2015). "The exome of CD46 were sequenced in 95 Finnish women with severe preeclampsia." (PMID 25710174, 2015). "We did not discover any association between A304V or other CD46 SNPs and preeclampsia." (PMID 25710174, 2015). "Studies on functional CD46 isoforms in preeclampsia may provide further insight into the possible role of MCP and complement-mediated injury in the pathogenesis of severe preeclampsia." (PMID 25710174, 2015). "The objective of this study was to investigate whether sequence variations in the CD46 promoter, splice sites and exome are present in Finnish women with and without preeclampsia." (PMID 25710174, 2015).
systemic lupus erythematosus (10 papers, 2011 to 2025). An autoimmune multi-organ disease typically associated with vasculopathy and autoantibody production. "Certain diseases, like autoimmune diseases, especially systemic lupus erythematosus and multiple sclerosis, are associated with increased concentrations of sCD46 indicating that stress-induced shedding of CD46 is not limited to hepatocytes." (PMID 39698100, 2024). "CD46 mutations have also been—albeit less consistently—linked to other immune-dysregulatory diseases, such as systemic lupus erythematosus (SLE), common variable immunodeficiency (CVID)-like antibody deficiency as well as pregnancy-related preeclampsia." (PMID 37477760, 2023). "Costimulation by CD3/CD46 proteins leads to IL-2 dependent Tr1-like cells with high IL-10 and low IFN-γ level production, which is associated with disease activity in lupus patients." (PMID 37771588, 2023). "The uncontrolled immune response of Th1 contributes to a wide range of lupus, and CD46 activation has emerged as a powerful controller of T cell-mediated immunity to contraction of Th1 immunity." (PMID 37771588, 2023). "Here, we report a defect in CD46‐regulated Th1 contraction in patients with systemic lupus erythematosus (SLE)." (PMID 28444759, 2017). "Elevated serum levels of CD46 have been reported in systemic lupus erythematosus (SLE)." (PMID 23864959, 2013). "lupus nTreg dysfunction is not due to intrinsic defect, but is induced by C3b stimulation of CD46 and IFN-α and these immune components of inflammation are directly associated with active lupus." (PMID 37771588, 2023). "Not surprisingly, perturbations in CD46 signals are connected with several autoimmune states characterized by Th1 hyperactivity, such as rheumatoid arthritis (RA), systemic lupus erythematosus (SLE), multiple sclerosis (MS), and scleroderma." (PMID 33717157, 2021).
autoimmune disease (9 papers, 2015 to 2024). A disorder resulting from loss of function or tissue destruction of an organ or multiple organs, arising from humoral or cellular immune responses of the individual to their own tissue constituents. "CD46 genetic variants are associated with susceptibility to several infectious and autoimmune diseases." (PMID 34831317, 2021). "Regulation of complement inhibitors (CD55, CD35, CD59, and CD46) is important in autoantibody-mediated complement activation and is impaired in autoimmune diseases such as SLE, rheumatoid arthritis, and bullous pemphigoid." (PMID 30473747, 2018). "CD46, a crucial complement regulatory protein in the complement activation, has been reported to be involved in several autoimmune diseases." (PMID 28273946, 2017). "CD46 and its role in certain diseases, including inflammatory diseases, allergy and autoimmune diseases, have attracted increasing attention over the past two decades." (PMID 28273946, 2017). "It has been reported that CD46 expression and function are impaired in some autoimmune diseases." (PMID 28273946, 2017). "Although one study connected mutations in CD46 with increased risk for onset of lupus nephritis 34 no work has so far been performed on the role for the sCD46 shed by (immune) cells in autoimmune disease." (PMID 28444759, 2017). "CD46 is a significant complement receptor protein that promotes human cytotoxic CD8+ T cell activity and relates with autoimmune diseases." (PMID 37953885, 2023). "Alternatively, this type of analysis may be useful in designing Ad11k/Ad21k-like proteins or Ad11k/Ad21k-derived peptide fragments to serve as inhibitors of CD46(SCR1-2) and complement activation, which would be useful in cases of autoimmune diseases." (PMID 26357573, 2015).
cervical carcinoma (9 papers, 2009 to 2025). A carcinoma arising from either the exocervical squamous epithelium or the endocervical glandular epithelium. "Univariate Cox regression analysis revealed that CD46 (P=0.034) is an independent risk factor for OS in cervical cancer patients." (PMID 38919630, 2024). "Therefore, our research findings strongly support the association between CD46 expression and cervical cancer development." (PMID 38919630, 2024). "CD46 shifts its expression profile in cervical cancer cells, compared to normal female reproductive tissue, suggesting its involvement in tumorigenesis." (PMID 40370471, 2025). "On the other hand, low CD46 expression rates in cervical cancer correlate with increased patient ́s survival." (PMID 40370471, 2025). "We also show that, like HeLa cervical carcinoma cells, conjunctival epithelial cells express four major spliceoforms of CD46 mRNA." (PMID 39772136, 2024). "In addition, we suggest that CD46 expression could serve as an independent risk factor for overall survival in cervical cancer patients, while sCD46 could be used as a potential biomarker for the diagnosis of cervical cancer." (PMID 38919630, 2024). "In conclusion, we showed that CD46 is generally overexpressed in cervical cancer tissues and that high CD46 expression, as determined by IHC, predicts a poor prognosis in patients with cervical cancer." (PMID 38919630, 2024). "Here, we show that HAdV-D64 can bind sialic acid and/or CD46 on immortalized human conjunctival epithelial cells and HeLa cervical carcinoma cells, two cell lines representative of targets of HAdVs D19, D37, and D64 infection." (PMID 39772136, 2024). "In this study, we showed that CD46 was significantly upregulated in cervical cancer tissues, while the soluble CD46 level was significantly greater in cervical cancer tissues than in healthy tissues." (PMID 38919630, 2024). "The data suggested that cervical cancer patients with high CD46 expression had significantly shorter OS than patients with low CD46 expression (P<0.05)." (PMID 38919630, 2024). "Consistent with previous data, our results suggested that high expression of CD46 was related to poor prognosis of cervical cancer." (PMID 35924232, 2022). "In cervical cancer, the inhibition of CD46 is reported to enhance complement-dependent cytolysis in cervical cancer cell line ME180." (PMID 33160404, 2020). "In consistent with the previous finding, our results suggested that CD46 is an independent prognostic factor for poor prognosis in cervical cancer." (PMID 33160404, 2020). "CD46 was expressed on the surface of all human cervical cancer cell lines and primary human cervical cancer cells: 97% in SiHa, 90% in C-33A, and 91–94% in CC-5 cells (n = 3)." (PMID 25909216, 2015). "The findings of this study may provide novel insights into the prognosis of patients with differential expression of CD46 who are receiving immunotherapy for cervical cancer." (PMID 38919630, 2024). "In combination with these findings and our previous studies in cervical cancer, the design of the present study suggest that CD46 may be an excellent target for antibody-based therapy development in cancers." (PMID 38919630, 2024). "After multivariate Cox regression analysis, eight genes were identified as key predictors of HLA-G-driven DEGs in the prognostic risk model for predicting the overall survival of patients with cervical cancer, including CD46, LGALS9, PGM1, SPRY4, CACNB3, PLIN2, MSMO1, and DAGLB." (PMID 35924232, 2022). "However, the clinical significance of CD46 in cervical cancer remains unclear, and this study aimed to evaluate its role in cervical cancer diagnosis and prognosis evaluation." (PMID 38919630, 2024). "In addition, our previous findings based on bioinformatics technology indicated that CD46 might be a key predictor of overall survival in cervical cancer patients that could be used in a prognostic model." (PMID 38919630, 2024).
cervical carcinoma (continued). "In addition, CD46 expression may be a survival pathway for cervical cancer cells to escape from tumor-specific CDC." (PMID 38919630, 2024). "CD46 expression in the normal human lung fibroblast cell line NHLF, human cervical cancer cell lines SiHa, C-33A and primary human cervical cancer cells of CC-5 was analyzed by flow cytometry." (PMID 25909216, 2015). "In this study, we focused on CD46 expression in plasma specimens, cervical cancer tissues and paired adjacent noncancerous tissues to evaluate the correlation between CD46 and clinical parameters." (PMID 38919630, 2024). "CD46 was found to be significantly upregulated in cervical cancer tissues vs. normal tissues, while no CD46 staining was detected in paired adjacent noncancerous tissues." (PMID 38919630, 2024). "Finally, among the 12 autophagy biomarkers related to the survival of cervical cancer, based on literature search, we selected 6 genes (ATG4C, ATG4D, CD46, TP73, SERPINA1 and HSPB8) to verify their RNA expression in CC and normal cervical tissue samples." (PMID 34238288, 2021). "The experimental results confirm that ATG4D, CD46, TP73 and HSPB8 are decreased in cervical cancer, and the prognosis model shows a negative correlation with the risk score, it could be inferred that they had a protective effect on the occurrence and prognosis of cervical cancer." (PMID 34238288, 2021).
hepatocellular carcinoma (9 papers, 2014 to 2025). A malignant tumor that arises from hepatocytes. "For example, in hepatocellular carcinoma cells, the relative density of CD46 is increased approximately 6-fold." (PMID 33147799, 2020). "CD46 acting as a complement regulatory protein contribute to escape of hepatoma cells from complement-dependent cytotoxicity." (PMID 31537905, 2020). "Studies have shown that expression of CD46 was decreased in hepatoma cells upon treatment with interferon-γ." (PMID 24297460, 2014). "CD46 expression is also upregulated in malignancies like hepatocellular carcinoma, possibly to escape complement-dependent cytotoxicity, but it remains unknown whether sCD46 titres are correspondingly elevated." (PMID 39698100, 2024). "Interestingly, we showed that HBx up-regulated CD59 and or CD46 to inhibit complement activation and protected hepatoma cells from complement attack in the development of HCC." (PMID 27050367, 2016). "Other cancers found to express higher levels of CD46 than adjacent normal tissues, which also relates to a worse clinical prognosis, include hepatocellular carcinoma (HCC), colon cancer, and Multiple Myeloma." (PMID 31164885, 2019). "Growing evidence has revealed that both the CD46 signaling pathway and microRNAs (miRNAs) play an important role in the development and progression of hepatocellular carcinoma (HCC)." (PMID 24297460, 2014). "Having identified several miRNAs that may be of value for the understanding of hepatoma development, here, we set out to compare miRNA expression patterns in CD46-overexpressed and -silenced HepG2 cell lines by applying microarray and qPCR profiling techniques." (PMID 24297460, 2014). "We previously found that HBx increased the complement regulation proteins such as CD46 and CD59 to protect hepatoma cells from complement attack." (PMID 27050367, 2016).
rheumatoid arthritis (9 papers, 2012 to 2022). A chronic, systemic autoimmune disorder characterized by inflammation in the synovial membranes and articular surfaces. "In consequence, C3 or CD46‐deficient patients suffer from recurrent infections while dysregulation of CD46 signaling contributes to Th1 hyperactivity in rheumatoid arthritis and multiple sclerosis." (PMID 28444759, 2017). "Defects in IL-10 production upon CD46 activation have been demonstrated in patients with MS, asthma and rheumatoid arthritis." (PMID 23144765, 2012). "Accordingly, patients deficient in CD46 cannot generate Th1 responses and suffer from recurrent infections, while dysregulation in this CD46/IL-2R crosstalk leads to a reduced IL-10 switching and hyperactive Th1 responses in rheumatoid arthritis (RA) and multiple sclerosis." (PMID 30700717, 2019). "Conversely, uncontrolled intracellular C3 activation leads to dysregulation of CD46-mediated stimulation of human T cells and contributes to pathologically hyperactive Th1 responses in rheumatoid arthritis (RA)." (PMID 28149297, 2017). "Dysfunctional CD46 signalling might also be implicated in the pathogenesis of rheumatoid arthritis (RA), where CD4+ T cells have a defect in the shutdown of IFNγ production following CD46 co-stimulation." (PMID 27739531, 2016). "When CD46 is dysregulated, this switch to a Treg phenotype does not occur, which clinically has been related to chronic inflammatory diseases such as relapsing and remitting Multiple Sclerosis (MS), asthma, and Rheumatoid Arthritis (RA)." (PMID 31164885, 2019). "Conversely, uncontrolled intracellular C3 activation and CD46 signalling leads to the dysregulation of human T cell responses and contributes to pathologically hyperactive TH1 cells in autoimmune disease (e.g., rheumatoid arthritis (RA))." (PMID 35860237, 2022).
glioma (8 papers, 2015 to 2025). A benign or malignant brain and spinal cord tumor that arises from glial cells (astrocytes, oligodendrocytes, ependymal cells). "To investigate the expression profile of CD46 in glioma, we analyzed CD46 expression across different glioma grades." (PMID 39955603, 2025). "The mRNA expression level of CD46 was highest in WHO IV gliomas, which represent the most malignant form of the disease." (PMID 39955603, 2025). "The chimeric fiber Ad5/35 adenovirus was utilized, which facilitates infection via the specific recognition of the CD46 receptor on the surface of tumor cells, as glioma cells highly express CD46." (PMID 39955603, 2025). "The expression of CD46 was significantly up-regulated in glioma tissues, particularly in high-grade glioma tissues (WHO III, WHO IV), when compared to normal brain tissue samples." (PMID 39955603, 2025). "To further examine the expression pattern of CD46 in glioma patients, we analyzed CD46 expression across different glioma grades." (PMID 39955603, 2025). "The attenuated MV strains have revealed tropism for infecting and killing glioma cells, due to the overexpression of the entry receptor CD46 on the cell surface of these cells." (PMID 33557101, 2021). "Although CD46 is abundantly expressed on glioma cells, facilitating efficient infection, some glioma cell lines show resistance to oncolysis after the viral entry, indicating that other processes can affect its oncolytic efficacy." (PMID 33557101, 2021). "MV, an enveloped RNA virus, exhibits the mutated hemagglutinin envelope glycoprotein H, also known as Edmonston strain, which selectively targets the CD46 on glioma cells." (PMID 34439595, 2021). "Targeting of glioma cells with survivin-driven CRAd improves upon retargeting of viral vectors to CD46 and/or DSG2 surface receptors as we detected in GBM3 primary glioma cells." (PMID 25738357, 2015). "We did not observe cytopathic effect or viral particle production after infection of glioma cells with wt MV, in contrast to the laboratory MV strain, which uses the ubiquitously expressed CD46 as entry receptor." (PMID 25710480, 2015). "We show that in glioma, MVs using CD133 and CD46 as receptors are particularly promising, while for HCC or other carcinomas not involving the central nervous system, VSV targeted to CD133 appears to be the best choice." (PMID 28695108, 2017). "First in our study we measured expression of primary receptors (DSG2, CD46 and CAR) in glioma cells." (PMID 25738357, 2015). "Additionally, flow cytometry analysis (FCAS) was performed to examine the expression of CD46 and the coxsackie-adenovirus receptor (CAR) in different glioma cell lines." (PMID 39955603, 2025). "In addition, we and others have confirmed that human glioma cell lines: U251, A172, U118, U87 and patient-derived GBM cells strongly express CD46." (PMID 25738357, 2015).